KRAS (KRas proto-oncogene, GTPase)
Diseases named in the same sentence as KRAS in open-access papers (continued):
Sharing a sentence is not in itself a finding about the gene and the disease.
cancer (continued). "Recent studies describe that the activation of KRAS signaling on cancer cells extends to the cancer microenvironment." (PMID 32850314, 2020). "Two cases of KRAS wild-type in the cancer panel examination appeared to have insufficient cancer cell content in ROSE." (PMID 31999789, 2020). "For instance, oncogenic KRAS induces several inflammatory cytokines, chemokines and signalling pathways that promote tumorigenesis and invasiveness in these cancers 13,14." (PMID 33116132, 2020). "One-third of human tumors are driven by RAS mutations, especially the KRAS isoform, whereas approximately 8% of tumors express an activated form of BRAF, accounting together for almost 40% of cancers." (PMID 32858836, 2020). "Another mechanism by which KRAS induces immunosuppression in cancer is via the induction of Tregs in the TME." (PMID 33116132, 2020). "Reductions in p-eIF4E level with a MNK1/2 inhibitor reduced the expression of PD-L1 in a MYC/KRAS model of cancer." (PMID 32759815, 2020). "Integration of both datasets resulted in the discovery of CDCP1 as a therapeutic antibody target for KRAS-driven cancer cells." (PMID 33036656, 2020). "To determine if miR181a1 and miR181b1 influence homeostasis of mutant-KRAS cancer cells, we used a CRISPR/Cas9-based knockout strategy using sgRNAs flanking the genomic region spanning the MiR181ab1 cluster." (PMID 31874105, 2020). "Allelic imbalance is frequent in KRAS mutant cancers and can enhance competitive fitness and modulate sensitivity to targeted therapies." (PMID 32990679, 2020). "It has been recently described that K-Ras4a is widely expressed in different types of cancers, indicating that differential expression can substantially influence KRAS signaling and regulation." (PMID 32524209, 2020). "Together, this suggests that β1-integrin+, EGFR+, Rab13+ sEVs are secreted by KRAS-mutant cancer cells, and that these vesicles play important roles in cancer development and progression." (PMID 32978434, 2020). "The investigation of this combination regimen further in other KRAS-induced cancers, particularly PDAC, would be beneficial." (PMID 33116132, 2020). "Lipids are an essential component of plasma membrane involved in cancer cell signaling and cancer metabolism and their role in KRAS-mediated cancers is emerging." (PMID 32594310, 2020). "Functionally, we demonstrate that a signaling cascade from ICMT modification of KRAS to TAZ protein stability supports cancer cell self-renewal abilities in both in vitro and in vivo settings." (PMID 32561852, 2020). "Activated oncogenic KRAS engages the PI3K/PDK1/AKT pathway to drive cancer initiation, progression, and maintenance." (PMID 32111094, 2020). "We aimed to develop a radiolabelled form of Oncrasin-1 to enable in-vivo imaging of mutant KRAS expression in malignant tumours." (PMID 33169204, 2020). "Oncogenic KRAS also markedly affects the glutamine pathway, which in cancer cells appears to play a pivotal role in nutrient dispensing." (PMID 32370075, 2020). "In this work, we approached three human oncogenes, BRAF, KRAS, and EGFR, and studied the mutation-specific probes as duplexes with a fragment of cancer RNA." (PMID 36703315, 2020). "We separated KRAS mutation, KRAS expression, PTPN2 expression, and clinical information of KRAS-related cancers from TCGA cohorts." (PMID 33122197, 2020).
cancer (continued). "In this analysis, patients with left-sided Kirsten rat sarcoma viral oncogene homolog (KRAS) wild-type disease were found to have better overall survival and progression-free survival than those with KRAS wild-type right-sided cancer." (PMID 33329946, 2020). "The amplicon 12p12.1 contains six genes other than BCAT1 (KRAS, LRMP, CASC1, LYRM5, and IFLTD1 and C12orf77), of which KRAS is a known cancer gene." (PMID 33488950, 2020). "We compared KRAS mutations between cancer gene panel testing by next-generation sequencing (NGS) and KRAS mutation analysis by polymerase chain reaction." (PMID 31999789, 2020). "We also provide evidence that SLIT2 can attenuate the growth of KRAS-transformed cancer cells by inhibiting macropinocytosis." (PMID 32807784, 2020). "One alternative strategy for developing KRAS targeted therapies is to identify downstream targets involved in promoting important malignant features, such as the acquisition of a cancer stem-like and metastatic phenotype." (PMID 32823550, 2020). "The future results would be important to explore the potential of IL-8 inhibitor combined with immunotherapy in KRAS-mutant cancers." (PMID 33116132, 2020). "The three RAS tissue specific isoforms (NRAS, neuroblastoma ras viral oncogene homolog; KRAS, Kirsten rat sarcoma viral oncogene homolog; HRAS, Harvey rat sarcoma viral oncogene homolog) are frequently mutated in cancers." (PMID 32850962, 2020). "Our results demonstrated that CRC cells transferred mutant KRAS protein to neutrophil and elevated formation of NETs increased secretion of IL-8 and in vivo as well as promoted proliferation of cancer cells in vitro." (PMID 32228650, 2020). "Overall, according to the COSMIC database, the prevalence of KRAS, HRAS and NRAS mutations is 23%, 3.41% and 7.51%, respectively, and varies in different cancer types." (PMID 32545208, 2020). "KRAS-transformed cancer cells use macropinocytosis to internalize large proteins, such as albumin, from their extracellular environment, to subsequently break them down into amino acids, which enter the cell metabolism to promote cancer cell survival." (PMID 32807784, 2020). "KRAS is the isoform most frequently altered in 86% of RAS mutant cancer cases, followed by NRAS 11% and HRAS 3%." (PMID 32560574, 2020). "Concomitantly, in cancer cells, TMPyP4-C14 decreases the expression of both KRAS and NRAS mRNAs and induces cell death upon photo-irradiation." (PMID 33198362, 2020). "Since it has been in the center of interest in oncotherapy for decades, there were many different approaches and strategies for targeting oncogenic RAS, with emphasis on the isoform that is most prevalent in cancer, namely KRAS." (PMID 32715349, 2020). "The concordance rate of KRAS mutations between cancer gene panel testing by NGS using ROSE specimens and KRAS mutation analysis by the companion diagnostics using residual materials was 81%." (PMID 31999789, 2020). "This study also demonstrated significant homology between canine and human cancers in terms of changes to known cancer-related signaling pathways including KRAS, PI3K/AKT, MAPK, PTEN and Wnt-β-catenin." (PMID 32411603, 2020). "RAS is a proto-oncogene that is mutated in human cancer, and the RAS protein is encoded by three expressed genes: Harvey-Ras (HRAS), Kirsten-RAS (KRAS), and neuroblastoma-Ras (NRAS)." (PMID 32486141, 2020). "These molecules were capable to selectively dissociate KRAS-G12V from the plasma membrane and inhibit the growth of KRAS-mediated cancers." (PMID 32770300, 2020).
cancer (continued). "Knowing that EVs from KRAS mutant cancer cells can induce KRAS wild type cells to proliferate and invade, James’ group pursues EV-driven modes of retina regeneration." (PMID 39698114, 2020). "A large portion of human cancers is characterized by mutations in genes encoding SWI/SNF subunits; furthermore, some oncogenes like MYC and KRAS can interact with SWI/SNF subunits promoting cancer progression in leukemia, lung and colon cancer cells." (PMID 33339101, 2020). "Further investigations will be needed to establish the role of oncogenic KRAS signalling on supercomplex assembly and respiratory efficiency and its possible impact on cancer." (PMID 31819197, 2020). "In particular, exosomes bearing KRAS G12D are released from cancer cells upon ferroptotic cell death, a type of autophagic cell death induced by oxidative stress." (PMID 32756339, 2020). "The use of vaccines, which are an active immunotherapeutic method for KRAS-mutant cancer, can overcome the binding problem of small molecule drugs and the difficulty of isolating and preparing TILs." (PMID 32903495, 2020). "In conclusion, our in vitro and in vivo data show that even though the KRAS degrader depletes both endogenous KRASWT and KRASMUT, it only inhibits cancer cells expressing mutant KRAS." (PMID 32591521, 2020). "These alterations are missense mutations that impair the ability of KRAS to hydrolyze GTP, resulting in the constitutive activation of its effector pathways and thus cancer development and progression." (PMID 32548736, 2020). "We found that KRAS mutation would worsen the CSS for patients with stage III and stage IV CRC, and for patients with cancers in the locations of left side colon and rectum." (PMID 32547859, 2020). "Among studies investigating the cooperation of KRAS and other factors in driving cancer initiation and progression the interplay between KRAS and CMYC has drawn attention." (PMID 32545208, 2020). "KRAS has been considered to be undruggable and there are currently no effective targeted therapies for patients with KRAS mutant cancers." (PMID 32397368, 2020). "An independent screen of 91 anti-cancer compounds highlighted several drugs targeting the DNA repair pathway as top hits in MCF10A KRAS G12D cells grown in minimal media including WEE1, CHK1/2 and PARP inhibitors." (PMID 32398776, 2020). "Owing to these results, we decided to investigate the genetic status of the KRAS gene in the three cancers by direct sequencing." (PMID 32867793, 2020). "Gene set overlap analysis for the respective sets of DEGs in HCT116 and RKO showed enrichment for genes in cancer-related signaling pathways such as KRAS, TNFA, and TGF-β for both RKO and HCT116 cell lines." (PMID 32471474, 2020). "Existing literature has demonstrated the potential of KRAS to regulate epithelial transition and proliferation of cancer cells through Wnt signaling pathway and MAPK signaling pathway, respectively, which help cure CRC patients by targeted therapy." (PMID 32228650, 2020). "Many molecular features that distinguish KRAS-dependent and KRAS-independent cancer cell lines have been uncovered." (PMID 32581224, 2020). "In contrast, under the same culture conditions KRAS/EGFR WT or KRAS mutant cancer cells are more sensitive to cisplatin than EGFR mutant cells." (PMID 32434541, 2020). "As such, it is in conjunction with the oncogenic KRAS when the presence of pathogens throws the Th1/Th2/Th17 cell ratio off balance and accelerates cancer progression." (PMID 32370075, 2020). "Due to its crucial role in cancer biology, KRAS is sometimes referred as the Holy Grail of drug discovery." (PMID 31988705, 2020). "The knowledge provided by the recent studies also helps to build the rational for the future design of combinatorial therapies for KRAS-driven cancers." (PMID 32397368, 2020). "These cancers have higher frequency of KRAS and BRAF mutations compared with conventional cancers, correlating to shorter overall survival." (PMID 32545410, 2020).
cancer (continued). "We also drew an SH model based nomogram for the cancer specific death prediction of CRC patients who had KRAS testing." (PMID 32547859, 2020). "Investigation of genes with decreased 5hmC in PDAC cfDNA as compared to non-cancer cfDNA indicated enrichment of genes downregulated when KRAS is up." (PMID 33077732, 2020). "Blood samples were obtained from cancer patients with defined driver gene hotspot mutations, including EGFR-T790M (n = 32), EGFR-L858R (n = 28), BRAF-V600E (n = 13), PI3KCA-E545K (n = 13), KRAS-G12C (n = 13), and KRAS-G12V (n = 6)." (PMID 32180799, 2020). "Recent studies have demonstrated that mutant KRAS-driven cancer cells bypass the glutamine-dependent late G1 checkpoint and arrest in S phase due to the lack of aspartate, presenting exciting opportunities for therapeutic intervention in KRAS-driven cancers." (PMID 32397368, 2020). "To determine the impact of PTPN2 expression in KRAS-related cancers, we analyzed clinical databases." (PMID 33122197, 2020). "Given the critical role of prenylation for KRAS membrane association and neoplastic transformation, and farnesylation of KRAS by FTase is the first step in the KRAS post-translational modification, FTase is the ideal target for KRAS-driven cancers." (PMID 33122197, 2020). "Recently, it was underscored that KRAS G12D is relayed from cancer cells to macrophages, indicating that KRAS G12D affects the cancer microenvironment." (PMID 32756339, 2020). "In this review, we discuss the crosstalk between oncogenic KRAS, inflammation and immune-modulatory mechanisms in cancer, with a focus on KRAS-induced NLRP3 inflammasome activation and programmed death-ligand-1 (PD-L1) expression." (PMID 33116132, 2020). "Unfortunately, KRAS G12C is only represented in a small fraction of RAS mutant cancers, and the challenge remains to drug the other RAS mutants." (PMID 31941155, 2020). "Ferritin, the main protein involved in iron binding and storage, regulates the intracellular LIP and its downregulation has been shown to increase LIP in KRAS-mutant cancer cells." (PMID 32393788, 2020). "Activating KRAS mutations and PTEN loss reportedly lead to PI3K/AKT pathway activation, independent of EGFR tyrosine kinase status, driving the downstream cancer survival pathways and supporting resistance." (PMID 32296588, 2020). "In other words, look for specific KRAS gene molecular signature associated with T2DM, and ultimately discover T2DM-specific approaches to prevent cancer-associated molecular evolution." (PMID 32939513, 2020). "Looking at GS enriched from AFB1-downregulated genes, a significant enrichment was observed for a GS related to cancer (“KRAS signaling dn”), which includes genes classically downregulated following KRAS activation." (PMID 32610656, 2020). "NGS allows to identify co-occurring genetic alterations in a specific subgroup of molecularly classified patients and better define the genomic complexity and the prognosis of patients with cancer, as in the case of KRAS mutant or EGFR mutant NSCLC tumors." (PMID 33333743, 2020). "Thanks to the use of NGS, co-occurring genetic alterations in genes other than KRAS, responsible for cancer cell proliferation, the development of escape mechanisms, and that impact on patients’ prognosis have been identified." (PMID 33333743, 2020). "Knockdown of Circ-MEMO1, prior to injecting cancer cells into nude mice, resulted in smaller tumors with increased miR-101-3P levels and decreased KRAS levels, relative to control targeted cells." (PMID 33172038, 2020).
cancer (continued). "Although there is a significant advance in the research of KRAS inhibitors, there are still many problems to be solved to finally develop an effective therapy for KRAS mutant cancers." (PMID 32715349, 2020). "Further, these results are consistent with RasV12Rare serving as a model of the rare codon bias of human KRAS, the most commonly mutated RAS family member in human cancers." (PMID 33296356, 2020). "In this study, we mined cancer genomics data and identified a common KRAS-driven gene signature in PDAC, which is related to cell–cell and cell–extracellular matrix (ECM) interactions." (PMID 32947833, 2020). "The concordance rate of KRAS mutations between cancer gene panel testing by NGS using ROSE specimens and KRAS mutation analysis by the Scorpion-ARMS or PCR-rSSO method using residual materials was 81% (21/26)." (PMID 31999789, 2020). "KRAS mutations have been implicated in approximately in nearly 40% CRC cases, as well as in many other types of human cancers such as lung cancer, breast cancer, prostate cancer and etc.." (PMID 32228650, 2020). "Mutant KRAS promotes not only the proliferation of cancer cells but also the infiltration of immunosuppressive cells such as regulatory T cells (Tregs) and reduces the proportion of CD8+ T cells in tumors." (PMID 32903495, 2020). "In our pancreatic cells, particularly KRAS-responsive cells such as Pa16C, we identified many differentially methylated genes associated with stemness following KRAS knockdown, suggesting that KRAS could be involved in inducing stemness in cancer cells through PI3K/AKT." (PMID 32576853, 2020). "For instance, KRAS is a member of the RAS oncogene family, the most frequently mutated oncogene family in human cancers, has been linked to SG assembly." (PMID 33138914, 2020). "Next, to test the clinical relevance of miR181ab1 targets in mutant-KRAS patients, we unveiled an accurate list of putative targets in human cancer." (PMID 31874105, 2020). "Analysis of a large patient cohort, as well as the TCGA database, revealed that allelic imbalance of KRAS is very frequent (55%) in cancers." (PMID 32725342, 2020). "Our data highlight a potential role for PARP inhibitors in KRAS mutant cancers and warrants further investigation." (PMID 32398776, 2020). "As major regulators of cancer stemness, positive interactions between KRAS and YAP/TAZ have been observed in multiple cancers." (PMID 32561852, 2020). "Our findings reveal that FMD cycles selectively potentiate vitamin C anti-cancer effect against KRAS-mutant tumors, both in vitro and in vivo, by reverting the vitamin C mediated upregulation of HO-1." (PMID 32393788, 2020). "An alternative approach to direct targeting of KRAS-mutant cancer genes involves targeting co-dependent vulnerabilities or synthetic lethal partners that are preferentially essential for KRAS oncogenesis." (PMID 32548736, 2020). "Consistent with the vitamin C-dependent production of H2O2, we observed the same selective increase in ROS in KRAS-mutant cancer cells grown in STS condition and treated with H2O2." (PMID 32393788, 2020). "In pancreatic Panc-1 cancer cells, an increase of oxidative stress enhances the level of 7,8-dihydro-8-oxoguanine (8OG) more in the KRAS promoter region containing G4 motifs than in non-G4 motif G-rich genomic regions." (PMID 32872305, 2020).